P3H1 (prolyl 3-hydroxylase 1)
Description:
Has prolyl 3-hydroxylase activity and catalyzes the post-translational formation of 3-hydroxyproline in -Xaa-Pro-Gly-sequences in pro-collagen chains, a critical step for the formation of mature collagen trimers. May be involved in the secretory pathway of cells. Has growth suppressive activity in fibroblasts.
Synonyms: GROS1; LEPRE1; LEPRECAN; MGC117314; OI8
Tractability: Small molecule: a structure with a bound ligand is known. Antibody: UniProt places it where antibodies can reach, with medium confidence; UniProt predicts a signal peptide or a membrane-spanning region; its Gene Ontology location is reachable by antibodies, with medium confidence. PROTAC: ubiquitination databases record sites on it.
Gene: Protein-coding gene on chromosome 1 (42,746,335 to 42,767,084, reverse strand). Ensembl gene ENSG00000117385.
Subcellular location: Endoplasmic reticulum (Isoform 1); Secreted, extracellular space, extracellular matrix
Subcellular location (Human Protein Atlas): Vesicles; Nucleoli
Pathways (Reactome):
Extracellular matrix organization: Collagen biosynthesis and modifying enzymes
Gene Ontology:
Molecular function: procollagen-proline 3-dioxygenase activity; protein binding; collagen binding; iron ion binding; L-ascorbic acid binding; oxidoreductase activity, acting on paired donors, with incorporation or reduction of molecular oxygen
Biological process: bone development; negative regulation of post-translational protein modification; protein folding; protein stabilization; regulation of protein secretion; collagen metabolic process; negative regulation of cell population proliferation; positive regulation of neuron projection development
Cellular component: endoplasmic reticulum; extracellular exosome; extracellular matrix; membrane; endoplasmic reticulum lumen; protein-containing complex
Genetic constraint (gnomAD): Loss-of-function variants: 75 observed, 86.63 expected, observed/expected ratio (o/e) 0.87, 90% interval 0.72 to 1.05. The upper end of that interval is the gene's LOEUF score, 1.05, which puts it in group 4 of 6, group 1 being the genes least tolerant of losing a copy. Missense variants: 876 observed, 958.54 expected, observed/expected ratio (o/e) 0.91, 90% interval 0.86 to 0.97. Synonymous variants: 365 observed, 387.74 expected, observed/expected ratio (o/e) 0.94, 90% interval 0.86 to 1.03.
Homologues: Orthologues: macaque P3H1 (98% identical), chimpanzee P3H1 (94% identical), rabbit P3H1 (91% identical), dog P3H1 (90% identical), guinea pig P3H1 (90% identical), mouse P3h1 (88% identical), rat P3h1 (88% identical), pig P3H1 (78% identical), tropical clawed frog p3h1 (67% identical), zebrafish p3h1 (53% identical). Paralogues in human: P3H2 (48% identical), P3H3 (42% identical).
Diseases named in the same sentence as P3H1 in open-access papers:
P3H1 is named in the same sentence as 34 diseases in open-access papers, as found by Europe PMC text mining. Sharing a sentence is not in itself a finding about the gene and the disease. The quoted sentences say what the papers report.
osteogenesis imperfecta (21 papers, 2010 to 2026). Osteogenesis imperfecta (OI) comprises a heterogeneous group of genetic disorders characterized by increased bone fragility, low bone mass, and susceptibility to bone fractures with variable severity. "Loss of P3H1 causes osteogenesis imperfecta, and P3H1 is consistently upregulated in idiopathic pulmonary fibrosis." (PMID 41932442, 2026). "Examples of relatively frequent ppIRAVs included the c.1473+5G>T variant at the 9th exon splice donor site of P3H1, linked with osteogenesis imperfecta." (PMID 36175409, 2022). "This heterozygous P3H1(LEPRE1) c.1224-80G>A variant wasidentified in a patient with osteogenesis imperfecta." (PMID 32123317, 2020). "P3H1 mutations can cause recessive osteogenesis imperfecta by forming abnormal collagen." (PMID 39777501, 2025). "Similarly, two patients were found to carry the same variant in the P3H1 gene causing autosomal recessive osteogenesis imperfecta." (PMID 32214361, 2020). "The complex is comprised of prolyl 3-hydroxylase 1, cartilage associated protein, and cyclophilin B. Mutations have been identified in the genes encoding the complex members in patients with recessive Osteogenesis Imperfecta." (PMID 24465224, 2014). "Mutations in CRTAP (coding for cartilage-associated protein), LEPRE1 (coding for prolyl 3-hydroxylase 1 [P3H1]) or PPIB (coding for Cyclophilin B [CYPB]) cause recessive forms of osteogenesis imperfecta and loss or decrease of type I collagen prolyl 3-hydroxylation." (PMID 20485499, 2010). "Mutations in the genes encoding cartilage associated protein (CRTAP) and prolyl 3-hydroxylase 1 (P3H1 encoded by LEPRE1) were the first identified causes of recessive Osteogenesis Imperfecta (OI)." (PMID 24465224, 2014). "Inactivating mutations in the P3H1-encoding gene LEPRE1 have been shown to cause a severe form of osteogenesis imperfecta characterized by decreased bone density, impaired mineralization and shortened long bones." (PMID 41278200, 2025). "Osteogenesis imperfecta (OI) types VII, VIII and IX, caused by recessive mutations in cartilage-associated protein (CRTAP), prolyl-3-hydroxylase 1 (P3H1) and cyclophilin B (PPIB), respectively, are characterized by the synthesis of overmodified collagen." (PMID 31171565, 2019). "At that time (2008) no potentially causative DNA change was found in COL1A1 or COL1A2, and so genetic analysis targeted regions of the CRTAP and P3H1 (previously named LEPRE1) genes, which had only recently been shown to cause recessive osteogenesis imperfecta." (PMID 29329516, 2018). "Since null mutations in either LEPRE1 or CRTAP can result in recessive forms of Osteogenesis Imperfecta (OI) with almost identical features, P3H1 and CRTAP were hypothesized to stabilize each other." (PMID 24465224, 2014). "Similarly, the p3h1, whose human ortholog is involved in osteogenesis imperfecta and p3h3 genes code for prolyl-3-hydroxylases, while the p4ha1a and the p4ha2 genes code for prolyl-4-hydroxylases whose mutation in mouse causes impaired ECM, chondrodysplasia, and kyphosis." (PMID 38547142, 2024). "Moreover, the role of CypB in bone development disorders, notably osteogenesis imperfecta (OI), has been researched: the Choi group found that severe OI develops in CypB KO mice, indicating the importance of the P3H1/CRTAP/CypB complex in collagen formation." (PMID 39045055, 2024). "The commonly affected genes in osteogenesis imperfecta include COL1A1, COL1A2, CRTAP, LEPRE1, PPIB, or P3H1." (PMID 34068971, 2021).
OI type VIII (6 papers, 2023 to 2025). "Elevated levels of serum TRAP were observed in OI type VIII patients with null mutations in P3H1 despite a normal osteoclast count." (PMID 40823439, 2025). "Of note, similar to LAPR6, the P3H1 protein was shown to be involved in the post-translational modification of collagen type 1 and is associated with collagen-related connective tissue disorders, in particular osteogenesis imperfecta type VIII." (PMID 39408753, 2024). "P3H1 variants are associated with OI type VIII, a severe or lethal form of OI, in which several dysregulated protein interactions may be involved." (PMID 36833249, 2023). "To investigate in vivo the effect of exogenous rHSP47 on the skeleton, we took advantage of the p3h1–/– zebrafish, recently generated and characterized in our laboratory as a valid model for recessive OI type VIII." (PMID 39913197, 2025). "Among others, OI type VIII is triggered by defects in prolyl 3-hydroxylase 1 (P3H1), a member of the endoplasmic reticulum (ER) resident prolyl 3-hydroxylation complex that is involved in the 3-hydroxylation of the α1(I)-Pro986 and in supporting collagen I triple helix folding and assembly." (PMID 40823439, 2025). "Alternative splicing of P3H1 resulting in the absence of functional P3H1 caused OI type VIII in 11 Thai children of Karen descent." (PMID 36833249, 2023). "However, the patient’s clinical phenotype was not consistent with osteogenesis imperfecta type 8 and a second relevant variant in P3H1 compatible with an autosomal-recessive trait was not demonstrable." (PMID 39276275, 2024).
breast carcinoma (3 papers, 2009 to 2024). "Immunohistochemical staining further validated our molecular findings, showing higher expression of P3H1/3 in breast cancer (BC) tissues and increased levels of P3H1 and CRTAP in liver cancer (LIHC) tissues." (PMID 38706607, 2024). "Studies have linked differential expression of P3H family members to cancer prognosis, such as the association of P3H1 with various tumors and elevated P3H2 and P3H3 levels in aggressive breast cancer." (PMID 38706607, 2024). "Here, while this study founded an up-regulation in the expression of prolyl 3-hydroxylase 1 in stage 2 of breast cancer tissue compared with normal tissue, reported the down-regulation of this protein." (PMID 31945087, 2020). "Using RT–PCR, we analysed the expression of the P3H1, P3H2 and P3H3 genes in breast carcinoma cell lines." (PMID 19436308, 2009). "This study examined the epigenetic regulation of P3H1, P3H2 and P3H3 expression in breast cancer cell lines and in a panel of breast carcinomas." (PMID 19436308, 2009). "Expression of P3H2 (Leprel1) and P3H3 (Leprel2) but not P3H1 (Leprecan) is down-regulated in breast cancer by aberrant CpG methylation in the 5′ regulatory sequences of each gene." (PMID 19436308, 2009). "To address whether promoter methylation was the cause of loss of gene expression, we performed MSP analysis of the CpG islands of P3H1, P3H2 and P3H3 in each of the breast cancer cell lines." (PMID 19436308, 2009).
Bruck syndrome (2 papers, 2020 to 2025). Bruck syndrome is characterized by the association of osteogenesis imperfecta and congenital joint contractures. "Three patients were identified with mutations in the P3H1, LEPRE, CRTAP, SERPINF1, PLOD2 (Bruck syndrome), TGFB1, and SGMS2 genes (Calvarial Doughnut Lesions with Bone Fragility)." (PMID 39941180, 2025).
liver cancer (2 papers, 2022 to 2024). An epithelial or non-epithelial malignant neoplasm that arises from the liver. "Knockdown of P3H1 significantly inhibited proliferation, migration, and invasive activity in liver cancer cells." (PMID 36339646, 2022). "And knockdown of P3H1 significantly reduced liver cancer cell proliferation, migration, and invasion in liver cancer cells." (PMID 36339646, 2022). "We further confirmed the role of P3H1 in liver cancer cells." (PMID 36339646, 2022). "In addition, the ability of proliferation, migration, and invasion was significantly downregulated in liver cancer cells with P3H1 knockdown." (PMID 36339646, 2022). "The experiments revealed that P3H1 can be involved in liver cancer progression." (PMID 36339646, 2022).
chondrosarcoma (1 paper, 2022). A malignant cartilaginous matrix-producing mesenchymal neoplasm arising from the bone and soft tissue. "Specifically, the highest levels of P3H1 were observed in chondrosarcoma and giant cell tumor cell lines, while colorectal and bile duct cell lines showed the lowest levels." (PMID 36339646, 2022).
colorectal cancer (1 paper, 2024). A primary or metastatic malignant neoplasm that affects the colon or rectum. "Additionally, P3H1 is closely associated with various tumors, particularly LIHC, and plays a role in extracellular matrix remodeling and immune suppression in colorectal cancer cells." (PMID 38706607, 2024).
diffuse large B-cell lymphoma (1 paper, 2022). "We revealed that patients with high P3H1 methylation levels presented a better prognosis in ACC, diffuse large B-cell lymphoma, glioma, LIHC, and melanoma." (PMID 36339646, 2022).
growth deficiency (1 paper, 2023). "Our patients, like most patients with P3H1 pathogenic variants, had growth deficiency, a very low bone mineral density, and bulbous metaphyses." (PMID 36833249, 2023).
rectal cancer (1 paper, 2022). A primary or metastatic malignant neoplasm that affects the rectum. "Bioinformatic analysis revealed a significantly higher expression of P3H1 in almost all tumors, which was consistent with the immunohistochemical findings in the liver, gastric, colon, pancreatic, and rectal cancers." (PMID 36339646, 2022). "And immunohistochemistry was utilized to verify the P3H1 expression in liver, gastric, colon, pancreatic, and rectal cancer." (PMID 36339646, 2022).
Rhizomelia (1 paper, 2014). Disproportionate shortening of the proximal segment of limbs (i.e. the femur and humerus). "CRTAP and P3H1 are mutually supportive in the complex; deficiency of either component causes severe to lethal OI with rhizomelia, classified as OI types VII and VIII, respectively." (PMID 24968150, 2014). "However, in contrast to Crtap and P3H1 null mice, Ppib−/− mice do not have rhizomelia." (PMID 24968150, 2014).
cancer (10 papers, 2009 to 2024). A tumor composed of atypical neoplastic, often pleomorphic cells that invade other tissues. "The elevated expression of most P3H family genes in cancer samples suggests an increased risk, particularly for P3H1, which is associated with poorer overall survival in several cancers." (PMID 38706607, 2024). "P3H1 expression was associated with overall survival, progression-free interval, disease-specific survival, and disease-free interval in most cancers, particularly in LIHC." (PMID 36339646, 2022). "Earlier research has suggested that P3H1 may act as a cancer-causing gene and serve as a separate indicator of unfavorable prognosis in BRCA." (PMID 38706607, 2024). "Moreover, P3H1 may be associated with the immunosuppressed state of other malignant tumors." (PMID 37081465, 2023). "It is worth noting that although we have provided a comprehensive analysis of the role of P3H1 in pan-cancer, there are still some restrictions." (PMID 36339646, 2022). "SERPINH1 and P3H1 both correlated negatively with tumor purity and positively with CD8+ T cells, B cells, macrophages/monocytes, dendritic cells (DC), cancer associated fibroblasts (CAF), endothelial cells, neutrophils, and natural killer (NK) cells." (PMID 34880916, 2021). "We estimated the relationship of P3H1 with 33 cancers using publicly available databases." (PMID 36339646, 2022). "The expression of P3H1 in various cancer cell lines was estimated using the CCLE database." (PMID 36339646, 2022). "In this study, we performed a systematic analysis of P3H1 in pan-cancer." (PMID 36339646, 2022). "In this study, bioinformatic analysis was performed to estimate the P3H1 expression in 33 cancers and its possible link to cancer, which was further verified by immunohistochemistry and in vitro experiments, to better understand the importance of P3H1 in multiple cancers, especially in LIHC." (PMID 36339646, 2022). "The Proline 3-hydroxylase (P3H) family, which includes P3H1, P3H2, P3H3, P3H4, and CRTAP, has garnered attention in cancer research due to its role in hydroxylating proline residues in collagen." (PMID 38706607, 2024). "ASPH, CDKN2A, E2F1, P3H1, and PTTG1 were identified as prognostic indicators of unfavorable outcomes within multiple cancer types." (PMID 37497116, 2023). "We have only confirmed P3H1 expression in LIHC, STAD, COAD, READ, and PAAD at the tissue level, as well as the role of P3H1 in LIHC at the cellular level, whereas the role of P3H1 in other cancers will require more research." (PMID 36339646, 2022). "P3H1 was expressed in all 13 carcinoma cell lines in our panel, but there was no detectable expression of P3H2 mRNA in MDA MB 361, MDA MB 453, MCF7 and T47D cell lines, with only low levels of expression in BT474 and SKBR3." (PMID 19436308, 2009).
tumor (9 papers, 2012 to 2024). "The results showed that P3H1 was expressed in all 38 kinds of tumor cell lines at different expression levels." (PMID 36339646, 2022). "Chi-squared analysis showed that patients with III-IV stage (P=0.037), poor tumor differentiation (P=0.047), and larger tumor size (P=0.021) exhibited a higher expression of P3H1." (PMID 36339646, 2022). "Here, we analyzed the impact of P3H1 methylation of the gene body on the prognosis of tumor populations." (PMID 36339646, 2022). "In our analysis, high expressions of SERPINH1 and P3H1 were found to correlate positively with immune infiltration and immune checkpoints in the tumor microenvironment." (PMID 34880916, 2021). "We found that P3H1 was significantly overexpressed in most tumor types." (PMID 36339646, 2022). "Besides, western blotting was performed and the results also showed that P3H1 expression was remarkably higher in tumor tissues." (PMID 36339646, 2022). "After finding that P3H1 could affect the malignant behavior of tumor cells, we further explored whether P3H1 was correlated with immune cell infiltration." (PMID 36339646, 2022). "P3H1 in LIHC has been shown to be closely connected to tumor development." (PMID 36339646, 2022). "The results were displayed a heatmap, which showed the expression levels of P3H1, SPP1, MMP1, LGALS1, and ITGB5 in tumor tissues and normal tissues." (PMID 32951492, 2020). "Finally, we also found that P3H1 expression in the presence of tumors was higher in ACC, BLCA, KIRC, LGG, MESO, and PRAD when compared to tumor-free status." (PMID 36339646, 2022). "Finally, we compared the difference in P3H1 expression between tumor tissues and adjacent nontumor tissue using the TCGA data." (PMID 36339646, 2022).
genetic diseases (1 paper, 2018). "Mutations in CRTAP, P3H1 and P3H2 cause human genetic diseases." (PMID 30417103, 2018).
P3H1 also shares sentences with these, for which no sentence is quoted: connective tissue disease (2 papers); hepatocellular carcinoma (2); osteosarcoma (2); acute myeloid leukemia (1); adenoma (1); bladder cancer (1); bone disorder (1); cholangiocarcinoma (1); Diabetes (1); fibrosis (1); fracture (1); giant cell tumor (1); glioma (1); idiopathic pulmonary fibrosis (1); leukemia (1); lung squamous cell carcinoma (1); melanoma (1); osteogenesis imperfecta type 1 (1); Pan (1); rheumatoid arthritis (1).